IL18 (interleukin 18)
Diseases named in the same sentence as IL18 in open-access papers (continued):
Sharing a sentence is not in itself a finding about the gene and the disease.
diabetes (continued). "Furthermore, these macrophages exhibited higher IL-15 and IL-18 expressions in individuals with diabetes and NASH (1.7-fold and 2-fold, both p < 0.05, respectively)." (PMID 40362271, 2025). "STZ-induced diabetes was associated with a significant decrease in the anti- inflammatory cytokine IL-10 and an increase in the proinflammatory cytokines CXCL-1, IFN-γ, IL-6, IL-18, and IL-33." (PMID 40649891, 2025). "Subgroup analysis revealed that the correlation between IL‐18 and the risk of adverse clinical events was not significantly affected by factors such as age, sex, history of diabetes, smoking, Gensini score, or ACS type (all p interaction >0.05)." (PMID 38402570, 2024). "The significantly high level of IL-18 detected in our patients could be related to diabetes itself or lichen planus." (PMID 38918874, 2024). "Liraglutide decreased expression of NLRP3, IL-18, and IL-1β in mice and pigs with diabetes." (PMID 41424495, 2024). "The model to predict SF-12 physical at 6-months had an R2 = 0.31 and included IL-1β as a significant predictor (p = 0.00), IL-18 (p = 0.05), the interaction of obese BMI and IL-1β (p = 0.04), and diabetes (p = 0.02), and reporting comorbid diabetes worsened SF-12 physical score at 6-months." (PMID 38702410, 2024). "Elevated IL-18 levels could be related to the pro-inflammatory autoimmune process in LP as well as the associated OLP, HCV, diabetes and hypertension." (PMID 38918874, 2024). "We detected higher level of IL-18 among patients with diabetes and hypertension." (PMID 38918874, 2024). "The condition is linked to higher levels of IL-18, TNF-α, and IL-6, indicating inflammation that may drive type 2 Diabetes Mellitus (T2DM)." (PMID 40027364, 2024). "Liraglutide decreased expression of NLRP3, IL-18, and IL-1β pigs and mice with diabetes." (PMID 41424495, 2024). "In addition, lower levels of inflammatory factors, including IL-1β and IL-18, were detected by ELISAs in the retinas of EC FtoΔ/Δ mice after introduction of diabetes." (PMID 37781923, 2023). "Pyroptosis, a type of programmed cell death characterized by cytoplasmic destruction, membrane pore formation, DNA fragmentation, and the release of the proinflammatory cytokines IL-1β and IL-18, is involved in various acute and chronic kidney diseases, including kidney injury in diabetes mellitus." (PMID 37261217, 2023). "In addition, the promoting effects of the miR-30e-5p inhibitor on IL-1β and IL-18 expression were dramatically reversed by ELAVL1 knockdown in the BMSC-exo-treated diabetes model cells." (PMID 36794663, 2023). "In response to the alkylating agent cyclophosphamide, macrophages from NOD mice presented an increase in IL-18 gene expression closely associated with diabetes development, while macrophages from Balb/c mice did not." (PMID 36313762, 2022). "The NLRP3 inflammasome and its products IL-1β and IL-18 may be potential targets for diabetes therapy." (PMID 36012516, 2022). "The effects of chitosan on the IL-18 expression in diabetes need to be further explored." (PMID 36547931, 2022). "Therefore, 12 weeks of Tai Chi intervention can significantly decrease the expressions of NEK7, NLRP3, ASC, Caspase-1, GSDMD, IL-1β, and IL-18, while increasing the expression of irisin in pre-diabetes." (PMID 36248820, 2022). "Diabetes induced cardiomyocyte hypertrophy, cardiac hypertrophy, interstitial fibrosis, oxidative stress, and cardiac contractile dysfunction, and increased gasdermin-D-N, and IL-18 expression in myocardial tissue." (PMID 36320147, 2022). "Moreover, elevated levels of C-reactive protein (CRP), tumor necrosis factor-α (TNF-α), IL-6, IL-18, and IL-1β were reported among patients with type 2 diabetes mellitus displaying features of the insulin resistance syndrome." (PMID 34917685, 2021).
diabetes (continued). "Although IL-18 was significant in the crude model (P = 0.02), after adjusting for potential confounders including age, gender, physical activity, smoking, alcohol consumption, and familial history of diabetes, this significance was disappeared (p = 0.06)." (PMID 34354158, 2021). "Even though various reports about diabetes and hypertension influencing dengue severity have been reported before, we are the first to report the significant increase of the IL-18 level in dengue-infected patients with comorbidities to dengue-infected patients without comorbidities." (PMID 34734091, 2021). "A study was conducted to investigate whether IL-18 promoter-607 C/a polymorphism affects serum IL-18 concentration and glucose metabolism in Chinese subjects through 232 patients with impaired glucose regulation (IGR) or type 2 diabetes mellitus." (PMID 31835423, 2019). "The effects of IL-18 -607 genotypes on the risk for RCC appeared to be protective among subjects without diabetes, but not among those with diabetes." (PMID 30925760, 2019). "Inflammation from continuously increasing IL-1β and IL-18 in diabetes patients could also lead to retinal and kidney lesions." (PMID 30555415, 2018). "Retinol-binding protein 4 (RBP4) expression was enhanced in patients with diabetes and its increase was correlated with retinal neuronal degeneration, early-onset of microglia activation and increased expression of pro-IL-18 and activated IL-18." (PMID 29301251, 2018). "This process is very active during diabetes, leading to IL-1 and IL-18 gene expression." (PMID 28708885, 2017). "NLRP3, caspase-1, IL-1β, and IL-18 were minimally expressed in normal glomerular tissues, but were significantly up-regulated in diabetic apoE (-/-) and apoE (-/-) mice, with more prominent changes in diabetes apoE (-/-) mice." (PMID 28708885, 2017). "Diabetes mellitus, age ≧ 50 years, IL-18 ≧ 804.3 pg/ml, IL-6 ≧ 3.92 pg/ml, and IL-1ß ≧ 0.86 pg/ml." (PMID 28474577, 2017). "Because TTP is known to regulate the expression of multiple cytokines via its ability to bind to AREs, the expression of TTP at an early stage of disease is consistent with the possibility that decreased TTP expression precedes and regulates increased IL-18 and IL-6 in diabetes." (PMID 26517838, 2015). "IL-12 and IL-18 may have direct or indirect impact on regulatory T cell subset, which may contribute to their reduced frequency in peripheral blood of patients with type 1 diabetes mellitus." (PMID 24677179, 2014). "In addition, serum IL-18 levels were elevated in patients with diabetes mellitus and diabetic nephropathy, which were in the state of low grade inflammation (microinflammation)." (PMID 24349077, 2013). "This suggests that β-NGF is a pro-inflammatory protein and index of inflammatory process related to chronic infection leading to cirrhosis and then to cancer, whereas glucagon and IL-18 are mainly due to diabetes that occurs as part of the metabolic syndrome with an increased risk of HCC." (PMID 22745767, 2012). "In summary, higher circulating levels of IL-18 were associated with increased MetS scores and systemic inflammation, which was independent of the presence of diabetes or dyslipidemia." (PMID 21251304, 2011). "The covariates entered into the model were IL-18 9545 genotype, age, gender, duration of bypass, pre-operative ejection fraction and whether the patient had diabetes or renal dysfunction." (PMID 19178691, 2009). "Importantly, aerobic exercise was unveiled to activate irisin, thereby inhibiting NLRP3/IL-18 and its subsequent inflammatory response and glycolipid metabolism, which provides effective approaches for the management of diabetes by using aerobic exercise intervention." (PMID 41264598, 2025).
diabetes (continued). "In diabetes-induced renal injury, caffeic acid protects renal function by reducing serum creatinine and blood urea nitrogen and inhibiting the production of inflammatory cytokines (such as IL-1β, IL-18, IL-6, and TNF-α) and the expression of NLRP3 inflammasome." (PMID 40909020, 2025). "Therefore, IL-18 may play an important role in diabetes-induced IVDD, although the detailed mechanisms need to be further investigated." (PMID 36186138, 2022). "Additionally, OPN with other reported inflammatory cytokines particularly IL-6, IL-8, IL-18, IL-1β, TNF-α, and serum CRP have been implicated in hypertension associated with diabetes via mediating the vascular effects of both angiotensin II (Ang II) and aldosterone, respectively." (PMID 34917685, 2021). "Therefore, serum IL-18 level may be a predictor of both cardiovascular diseases and renal outcome in patients with type 2 diabetes mellitus." (PMID 32487168, 2020). "Interleukin (IL)-17A and IL-18 have been proposed to play important roles in periodontitis and type 2 diabetes mellitus (DM), but human data are conflicting." (PMID 32053656, 2020). "In addition, in the case of IL-18 and IL-6, the increased secretion of these cytokines under the influence of LPS in the group with diabetes may be the result of the increased production of these factors in the slices under basal conditions." (PMID 31197747, 2019). "We further conducted stratification analysis of the association between IL-18 -607 genotypes and the risk for RCC based on potential personal behavioral and clinical risk factors among Taiwanese people, including cigarette smoking, alcohol consumption, hypertension, and diabetes status." (PMID 30925760, 2019). "However, the strong correlations between IL-18 and hsCRP, IL-6 and IL-1RA in patients with T2D in contrast to their absence in T1D point towards differences in the regulation and/or the pathophysiological relevance of this cytokine between both diabetes types." (PMID 29520075, 2018). "We postulated that TTP might regulate interleukin (IL)-6 and IL-18 expression in diabetes." (PMID 26517838, 2015). "In Caucasian subjects with CAD, the G allele of the interleukin 18 (IL18) gene +183 A/G polymorphism is associated with significantly reduced serum IL-18 levels in subjects with type 2 diabetes (n = 200) compared to subjects without diabetes." (PMID 22533709, 2012). "Significantly high levels of IL-18 was found among female patients, HCV + ve patients and patients suffering from diabetes mellitus (DM) and hypertension." (PMID 38918874, 2024). "In our study, when patients with a diagnosis of diabetes were evaluated, it was noted that the majority of them were using metformin, as monotherapy or in combination with sitagliptin, or insulin, and we assume that the lower levels of IL-18 and hsCRP might be related to this treatment." (PMID 37763063, 2023). "Regarding diabetes, it has been reported that inflammatory factors such as TNF-α, IL-1ß, IL-6, and IL-18 are increased in diabetic patients, contributing to insulin resistance through the JNK and IKKb/ NFkB pathways." (PMID 36832168, 2023). "In addition, it is worth mentioning that researchers have recognized the relationship between IL-18 and IL-1β secretion, which significantly increases the expression of IL-1β, suggesting that IL-18 may promote the development of diabetes through its interaction with IL-1β." (PMID 37868953, 2023). "IL‐18 pathway can be blocked by targeting IL‐18 with two drugs (GSK1070806, MEDI‐2338) in clinical trials positioned for Diabetes mellitus and COPD respectively." (PMID 37186423, 2023). "Systemic administration of IL-18 also promoted diabetes development in young NOD mice, while endogenous IL-18 was required to observe the full diabetogenic effect of streptozotocin in C57BL/6 mice." (PMID 36313762, 2022). "However, the function of elevated IL-18 in diabetes-induced IVDD remains unknown." (PMID 36186138, 2022).
diabetes (continued). "Diabetes promoted the decrease of LC3-II content, increased the p62, NLRP3, gasdermin-D-N, and IL-18 levels in myocardial tissue." (PMID 36320147, 2022). "In the urine, significantly higher IL-18 concentrations were found in type 2 diabetes mellitus and DKD compared to healthy controls, and IL-18 correlated with markers of podocyte and proximal tubule dysfunction." (PMID 35204131, 2022). "Diabetes aggravated adverse cardiac remodeling, increased the mortality rate, cardiac hypertrophy, the fibrotic area, and enhanced IL-1β, IL-6, TNF-α, and IL-18 expression in myocardial tissue." (PMID 36320147, 2022). "Diabetes resulted in an increase in NLRP3 content in atrial tissue, a rise in the serum IL-1β and IL-18 concentrations." (PMID 36320147, 2022). "Moreover, in another animal model of diabetes, short-term prophylactic treatment with inhibitors of IL-18 (IL-18Bp-Fc-fusion molecule) significantly protected animals from developing overt diabetes, further strengthening the evidence suggesting the role of IL-18 in T1D." (PMID 36032110, 2022). "Diabetes patients’ recorded increased levels of OPG, RANKL, TNF-α, MMP-9, IL-18 and TOS compared to controls both pre- and post-extraction." (PMID 34829612, 2021). "The activation of diabetes-mediated related factors such as TLR4, NLRP3, caspase-1, IL-1β, IL-18, and GSDMD-NT plays a vital role in the pathophysiology of DKD." (PMID 33692782, 2021). "Furthermore, a comparison of melioidosis patients based on diabetes status alone revealed significantly higher levels of IL‐18 (p < 0.0001) and IL‐18BPa (p < 0.0001) in the circulation of DM compared to non‐DM patients with acute melioidosis." (PMID 31032897, 2019). "The current study shows that Lf decreased diabetes-induced inflammation by inhibiting the TLR-4-NF-κB axis with subsequent reduction in serum proinflammatory cytokines; IL-1β, IL-6, and IL-18, in diabetic children." (PMID 30534206, 2018). "In this study, IL-18, TNF- α and IL-6 had positive correlation with the degree of diabetes control and is similar to what had been observed in other studies." (PMID 28577020, 2017). "PIO significantly attenuated the diabetes-induced activation of the NLRP3 inflammasomes and their downstream effectors, including caspase-1, IL-1β, and IL-18." (PMID 28708885, 2017). "During the progression of diabetes, CB1 promotes the Nlrp3-ASC inflammasome activation and the release of IL-1β and IL-18 in infiltrating macrophages, which act as paracrine signals to induce beta cell apoptosis." (PMID 29033935, 2017). "Since NLRP3 inflammasome regulates inflammatory pathways in diabetes, we examined serum amyloid A (SAA), a major prototypic marker of inflammation in rodents, as well as circulating levels of IL-1β and IL-18." (PMID 29435463, 2017). "IL-18 and TNF-α levels also correlated positively with the degree of albuminuria in the patients with diabetes." (PMID 26064987, 2015). "Serum and urinary levels of IL-6 and IL-18 were significantly elevated, but those of TTP were significantly decreased in patients with diabetes as compared with control subjects." (PMID 26517838, 2015). "Carotid intima-media thickness (IMT) measured by carotid ultrasound is a useful tool for assessing cardiovascular diseases in diabetes mellitus, and carotid IMT in patients with high IL-18 showed a greater thickness than in patients with normal IL-18." (PMID 24349077, 2013). "Increased levels of pro-inflammatory cytokines MCP-1, IL-1β, IL-6, IL-18 and TNF-α have been reported in diabetes." (PMID 24359406, 2013). "Clinically, high IL-18 levels in the circulation are purported to be predictors of cardiovascular mortality, ischemic stroke outcome, and a marker for insulin resistance (type 2) diabetes mellitus (DM)." (PMID 24555158, 2013). "The NLRP3 inflammasome activation and subsequent maturation and secretion of IL-1β and IL-18 initiated further pro-inflammatory events, producing kidney damage of STZ-induced diabetic rats." (PMID 22701621, 2012).
diabetes (continued). "Klotho, which mitigates diabetes-induced elevation of serum creatine kinase-muscle/brain (CK-MB) and LDH, cardiac fibrosis, cardiomyocyte apoptosis, and cardiac dysfunction, also inhibits NLRP3 activation and TNF-α, IL-1β, and IL-18 expression." (PMID 41399377, 2026). "This study demonstrates positive associations of CDCP-1, FGF-21, IL-8, IL-18, eotaxin/CCL11, MMP-10, TNFRSF9, CCL25 and IL-10RB with depressive symptoms in people with diabetes without interaction with diabetes type." (PMID 39799156, 2025). "Accordingly, we hypothesized that NLRP3 dysregulation might affect pyroptosis in diabetic ED and evaluated pyroptosis markers (GSDMD, GSDMD-N, pro-caspase-1, cleaved-caspase-1, ASC, IL-1β, and IL-18)." (PMID 39014129, 2024). "Inflammatory processes are initiated during diabetes, resulting in the formation of inflammatory molecules such as tumor necrosis factor α (TNF-α), interleukin 1β (IL-1β), interleukin 6 (IL-6), and interleukin 18 (IL-18)." (PMID 39684653, 2024). "In diabetes, hyperglycemia can stimulate the activation of NLRP3, thus activate Caspase-1, which can promote the maturation of cytokines pro-IL-1β and pro-IL-18 to release the cleaved fragments of active IL-1β and IL-18, and lead to pyroptosis." (PMID 39545058, 2024). "When the inflammatory parameters were re-evaluated according to the presence of concomitant diabetes, lower levels of IL-18 and hsCRP were detected in the presence of diabetes, but no significant change was observed in the NLRP3 and IL-1β levels." (PMID 37763063, 2023). "It is noteworthy that mice lacking caspase-1, despite having diminished IL-1 and IL-18 levels, demonstrated comparable diabetes incidence and streptozotocin sensitivity to regular mice." (PMID 37762961, 2023). "In diabetes patients significantly higher levels of circulating gp130 and higher expression of caspase-1 in EAT (p < 0.05, both) were found, and patients with previous myocardial infarction had higher circulating levels of IL-18 (p = 0.020)." (PMID 36644557, 2022). "In diabetes, the activation of NF-κB stimulates the transcription of NLRP3 and activation of the NLRP3 inflammasome, resulting in the cleavage of caspase-1, which increases the production of mature IL-1β and IL-18." (PMID 34997266, 2022). "However, when IL-18 was administered to 10 weeks old female NOD mice, exogenously, the mice were protected from diabetes." (PMID 36032110, 2022). "Diabetes triggered NLRP3, ASC, gasdermin-N, caspase-1, and collagen I expression in myocardial tissue, and promoted an increase in the serum TNF-α, IL-1β, IL-6, and IL-18 levels." (PMID 36320147, 2022). "Regular exercises have been shown to increase the release of anti-inflammatory cytokines and they lead to a reduction in pro-inflammatory cytokines, e.g., TNF-α and interleukin 1β (IL-1β), interleukin 6 (IL-6), interleukin 18 (IL-18), CRP, which play a role in the pathogenesis of diabetes." (PMID 36555387, 2022). "We observed that inflammatory markers (TNF-α and IL-18) protein expression was positively correlated with SRA1 protein expression in individuals without diabetes." (PMID 34685582, 2021). "TGF-β/IL18 independently predicted the SRA1 expression in people without diabetes and in the total study population, while TNF-α/IL-2RA predicted SRA1 only in people with diabetes." (PMID 34685582, 2021). "In support of this notion, IL18 has been proposed as a viable target in Mendelian enterocolitis, and an anti-IL18 antibody has been found to be safe in a Phase II trial of diabetes, albeit without efficacy." (PMID 34661200, 2021). "TGF-β and IL18 in people without diabetes and TNF-α and IL2RA in people with diabetes were independent predictors of SRA1 expression." (PMID 34685582, 2021). "Indeed, at 50 ng/mL, an up-regulation was only observed for IFNγ in response to the diabetes and CAD marker IL-18, but a reduction for at least one of the three T-cell activity markers in response to all other biomarkers except CX3CL1 and periostin." (PMID 34281240, 2021).